PGGHG (protein-glucosylgalactosylhydroxylysine glucosidase)
Description:
Catalyzes the hydrolysis of glucose from the disaccharide unit linked to hydroxylysine residues of collagen and collagen-like proteins.
Synonyms: ATHL1; FLJ22635
Tractability: PROTAC: ubiquitination databases record sites on it.
Gene: Protein-coding gene on chromosome 11 (289,095 to 296,107, forward strand). Ensembl gene ENSG00000142102.
Subcellular location (Human Protein Atlas): Cytosol
Gene Ontology:
Molecular function: protein-glucosylgalactosylhydroxylysine glucosidase activity; catalytic activity
Biological process: carbohydrate metabolic process
Cellular component: cytosol
Genetic constraint (gnomAD): Loss-of-function variants: 67 observed, 77.22 expected, observed/expected ratio (o/e) 0.87, 90% interval 0.71 to 1.06. The upper end of that interval is the gene's LOEUF score, 1.06, which puts it in group 4 of 6, group 1 being the genes least tolerant of losing a copy. Missense variants: 1,034 observed, 998.65 expected, observed/expected ratio (o/e) 1.04, 90% interval 0.98 to 1.09. Synonymous variants: 496 observed, 427.02 expected, observed/expected ratio (o/e) 1.16, 90% interval 1.08 to 1.25.
Homologues: Orthologues: chimpanzee PGGHG (99% identical), macaque PGGHG (91% identical), pig PGGHG (80% identical), dog PGGHG (77% identical), mouse Pgghg (73% identical), rat Pgghg (73% identical), guinea pig PGGHG (73% identical), tropical clawed frog pgghg (49% identical), zebrafish pgghg (42% identical), Drosophila melanogaster CG16965 (30% identical).
Diseases named in the same sentence as PGGHG in open-access papers:
PGGHG is named in the same sentence as 2 diseases in open-access papers, as found by Europe PMC text mining. Sharing a sentence is not in itself a finding about the gene and the disease.
PGGHG shares sentences with these, for which no sentence is quoted: multiple sclerosis (1 paper); tumor (1).